APC (APC regulator of Wnt signaling pathway)
Diseases named in the same sentence as APC in open-access papers (continued):
Sharing a sentence is not in itself a finding about the gene and the disease.
liver cancer (27 papers, 2008 to 2025). An epithelial or non-epithelial malignant neoplasm that arises from the liver. "CDC23, one of the APC subunits involving cell mitosis, was reportedly associated with cell cycle progression in liver cancer cell lines, since shRNA‐mediated knockdown repressed cell proliferation." (PMID 40022573, 2025). "In liver cancer, mutations or dysregulation of key components of the Wnt pathway, such as β-catenin, adenomatous polyposis coli (APC), and Axin, results in the constitutive activation of Wnt signaling, thereby promoting tumor progression." (PMID 38756274, 2024). "Accumulating studies have successively explored the role of APC hypermethylation in gastrointestinal (GI) tumors, such as in esophageal, colorectal, gastric, pancreatic, and hepatic cancer." (PMID 33968756, 2021). "The APC promoter was reported to be hypermethylated in about 64.91 to 84% liver cancer patients, which was significantly higher than the non-HCC group, and a strong association was detected between hypermethylation and the risk of suffering from HCC." (PMID 33968756, 2021). "Mutations to APC and CTNNB1 are the most frequent mutations in colon and liver cancer, respectively, and are thought to initiate cancer." (PMID 32486480, 2020). "GHJCD treatment, especially at a high concentration, significantly increased the expression of APC protein in the liver cancer microenvironment." (PMID 32547401, 2020). "Mutations in WNT/β-catenin pathway coding genes such as CTNNB1, AXIN and APC are found in colorectal and hepatic cancers and are known to drive tumorigenesis." (PMID 31412666, 2019). "For instance, colorectal and hepatic cancers display activating mutations in the CTNNB1 gene encoding β-catenin, or inactivating APC and AXIN gene mutations." (PMID 31412666, 2019). "Of the only five liver-cancer-associated genes from CGC, APC appeared as a recurrent hub in multiple subnetworks." (PMID 24564909, 2013). "Relevant studies show that P16, RASSF1A, GSTP1, APC, p15 and SFRP1 genes are significantly hypermethylation in HBV positive liver cancer." (PMID 38304027, 2023). "Interestingly, it has been previously reported in liver cancers that EZH2 repressed, in an H3K27me3-dependent manner, the APC promoter leading to the activation of the Wnt/β-Catenin pathway." (PMID 33291363, 2020). "and cancer driver genes (ATRX, MDC1, RIF1, APC and PCM1) showed a phosphorylation related signal transition network affecting cell proliferation ability and revealed the extreme complex nature of phosphoproteome transformation in liver cancer cells." (PMID 28883432, 2017). "In liver cancers, FZC18 immunostaining negatively correlates with Wnt/β−catenin signaling and with the protein expression of the β−catenin-regulated gene GS, consistently with the suppression of GS synthesis by DKK1 in mice carrying an APC disruption." (PMID 18382662, 2008).
lung adenocarcinoma (27 papers, 2013 to 2026). A carcinoma that arises from the lung and is characterized by the presence of malignant glandular epithelial cells. "Therefore, the APC methylation test could be a promising diagnostic biomarker which could be applied in the clinical diagnosis of lung adenocarcinoma with remote non-invasive media detection." (PMID 24661338, 2014). "According to recent studies, BCA2 promotes survival in lung adenocarcinoma cells by promoting Wnt/β-catenin signaling pathway activation through APC ubiquitination." (PMID 38725852, 2024). "Moreover, RNF115 overexpression promotes ubiquitination of adenomatous polyposis coli (APC) to modulate the Wnt/β-catenin pathway activation, and thereby promotes the proliferation and inhibits the apoptosis of lung adenocarcinoma cell lines." (PMID 35844553, 2022). "The APC methylation test could be applied in the clinical diagnosis of lung adenocarcinoma." (PMID 24661338, 2014). "Another interesting finding was the higher APC and RARβ2 methylation levels in patients with SCLC vs. lung adenocarcinoma." (PMID 30261643, 2018). "While for instance APC and CDH13 methylation was detected more frequently in lung adenocarcinomas compared to lung squamous cell carcinomas, p16 methylation was detected more frequently in lung squamous cell carcinomas than in lung adenocarcinomas." (PMID 28093071, 2017). "Five genes were flagged as mutant in all 8 lung adenocarcinoma samples namely RET, APC, FGFR3, NPM1 and PDGFRA when the least stringent QBVD threshold was applied (QBVDi = 71)." (PMID 23922754, 2013). "In lung adenocarcinoma, RNF115 could ubiquitinate APC and result in its degradation, thus regulating Wnt/β‐Catenin signalling to promote cellular proliferation." (PMID 37132043, 2023). "Results of cell lines and nude mouse studies showed us the dynamic changes of APC and RASSF1A methylation on both lung adenocarcinoma cell line (A549) and large cell lung cancer cell line (H460) and indicated that peak methylation increase is also at 24 h after cisplatin administration." (PMID 26550041, 2015).
esophageal cancer (26 papers, 2007 to 2026). A primary or metastatic malignant neoplasm involving the esophagus. "The pathogenic mechanism of APC reported for other tumors was mainly through truncated proteins caused by APC mutations, but these causative mutations reported for esophageal cancer have been rare." (PMID 33968756, 2021). "Quantification of circulating plasma DNA revealed that up to 61% of patients with esophageal carcinoma have detectable levels of methylated DAPK (Death-associated protein kinase) or APC (adenomatous polyposis coli gene) promoter DNA." (PMID 24065096, 2013). "While loss of heterozygosity along with mutational inactivation has been suggested for APC in esophageal cancer, nevertheless, mutations in APC are rare in this cancer." (PMID 19149902, 2009). "A similar repertoire as the esophageal cancers is also noted in the cancers of stomach although consisting of a different set of mutated genes (e.g. CDH1, APC, etc.)along with microsatellite instability." (PMID 40720480, 2025). "Till now, a clinical epidemiological survey has shown that esomeprazole can inhibit the methylation of tumour suppressor gene APC and increase the expression of APC in oesophageal cancer." (PMID 35961680, 2023). "Otherwise, APC hypermethylation has been observed in less advanced stages of both types of esophageal cancer, similar to p16 and hMLH1 genes." (PMID 19149902, 2009). "APC is among tumor suppressor genes whose inactivation occurs in esophageal cancer as well as other GI cancers." (PMID 19149902, 2009). "Since free intracellular β-catenin levels are tightly regulated by the cytoplasmic APC/Axin destruction complex, additional experiments were performed to examine the effects of proteosome inhibitors in esophageal cancer cells constitutively expressing A279T or wtTERT." (PMID 24983628, 2014). "This indicates that inactivation of APC plays a key role in the carcinogenesis of esophageal cancers and could be considered as a candidate molecular marker." (PMID 19149902, 2009). "In esophageal cancer, METTL3 and METTL14 act synergistically on APC mRNA, and the APC mRNA modified by m6A degrades after binding with YTHDF." (PMID 37582735, 2023). "Here the authors show that N6-methyladenosine methylation writer METTL3 downregulates APC by recruiting YTHDF2 for APC mRNA degradation, and that this promotes glycolysis and tumour growth in oesophageal cancers." (PMID 34155197, 2021). "For example, most of the genes on the trunk of sample ESCC12 (CCND1, EGFR, APC, TGFBR2, XPC, XPA, FLI1, and NUMA1) have been identified and initially reported on the esophageal cancer." (PMID 30540749, 2018). "The methylation levels of APC, ITGAV, PRDM16 and PTX3 were significantly different between esophageal cancer and healthy control tissues." (PMID 27893424, 2017). "Methylation-based markers researches for esophageal cancer have mainly been focused on hypermethylation in promoter region CpG island of numerous tumor suppressor genes, such as APC and CDKN2A, which thus were thought to be potential biomarkers for the diagnosis of BE and esophageal cancer." (PMID 31834866, 2019). "In esophageal cancer, the 5-year survival rate of high expression of PRR11 was significantly lower than that of the low expression group, which may be related to the interaction of PRR11 with destructive complexes (APC, GSK-3β and AXIN2) to activate the Wnt/β-catenin pathway." (PMID 34659555, 2021).
bladder cancer (25 papers, 2010 to 2025). "APC promoter methylation was detected in 34 (68%) of bladder cancer cases but in only eight (16%) of healthy controls, indicating a strong association between APC promoter methylation and bladder cancer (p < 0.001)." (PMID 39569232, 2024). "Other investigators have identified DNA methylation of RARbeta2 and APC as potential urine biomarkers of bladder cancer, with schistosomiasis-associated cases having higher rates of methylation of these genes." (PMID 26042665, 2015). "As discussed by Serizawa, results also showed that FGFR3 mutation in bladder cancer when combined with methylation markers (APC, RASSF1A and SFRP2) provided a sensitivity of 90% to identify bladder tumors." (PMID 22530128, 2012). "In a recent bladder cancer study FGFR3 mutation in combination with APC, RASSF1A, and SFRP2 methylation markers provided a sensitivity of 90% using tissue samples and 62% using paired urine samples to identify the presence of cancer with 100% specificity." (PMID 22530128, 2012). "Importantly, either APC mutations or nuclear β-catenin accumulation are associated with poor outcome in patients with invasive bladder cancer." (PMID 32282334, 2020). "A key focus is on proTAME, originally developed to target APC/C activity, to assess its potential for repurposing in bladder cancer treatment." (PMID 40136519, 2025). "These insights highlight the potential of targeting the APC/C pathway in combination with ECM-modulating agents to improve bladder cancer management." (PMID 40136519, 2025). "An additional study examined adenomatous polyposis coli (APC) promoter methylation as a potential urinary biomarker of bladder cancer." (PMID 40282460, 2025). "In a study of 113 bladder cancer cases, promoter methylation of p14ARF was detected in 38% of tumor tissues and 32% of urine samples, while APC methylation was observed in 54% of tissues and 46% of urine samples." (PMID 41438986, 2025). "Methylation-specific PCR was used to determine the methylation status of the APC promoter gene in 50 bladder carcinoma patients and 50 apparently healthy individuals." (PMID 39569232, 2024). "Since bladder cancer can be detected using a variety of panels, including RASSF1a/APC/p14, RAR /DAPK/E-cadh/p16, p16/p14/MGMT/GSTP1, and RASSF1a/E-cadh/APC, it is important to consider these panels." (PMID 36627997, 2022). "Previous studies have indicated that bladder cancer patients with APC or RASSF1A methylation show a trend toward poor survival." (PMID 21599969, 2011). "This study highlights the clinical utility of using a simple urine test to detect bladder cancer, particularly in early stages, and suggests that combining APC methylation with other specific biomarkers could enhance diagnostic accuracy." (PMID 39569232, 2024). "Promoter methylation of TNFRSF25, EDNRB, RASSF1A, and APC could even be used to anticipate which bladder cancer patients require routine surveillance versus immediate radical treatment." (PMID 29614786, 2018). "Moreover, higher methylation rates of RARbeta2 and APC genes have been observed in Schistosoma-associated bladder cancer compared to non-Schistosoma bladder cancer patients." (PMID 34885162, 2021). "This study aims to evaluate the combination effects of cisplatin, gemcitabine, and the APC/C inhibitor proTAME on cell migration as well as MMP2 and MMP9 expression in bladder cancer (RT4 cells) and normal epithelial cells (ARPE-19) as the control." (PMID 40136519, 2025). "Meanwhile, some tumor suppressor genes have been identified as direct and functional targets of miR-155, such as APC, VHL, PIK3R1, MLH1, all of where are frequently inactivated in bladder cancer due to promoter hypermethylation." (PMID 26657502, 2016). "The RNA expression of RASSF1A, APC and MGMT was also found to be decreased in the muscle-invasive high grade bladder cancer when compared to the non muscle invasive low grade group (p-value < 0.05)." (PMID 24790823, 2014).
bladder cancer (continued). "The proportion of cancers identified in HES APC but not in NCRAS is particularly high for bladder cancer." (PMID 32819994, 2020). "However, only APC and MGMT showed significance (p < 0.001) in the muscle invasive high grade bladder cancer when it was compared with the normal bladder mucosa." (PMID 24790823, 2014). "Urine could be a source of tumor DNA for detecting prostate and bladder cancer, though hypermethylation of glutathione S-transferase P1 (GSTP1) or other gene panels (e.g., RASSF1A, APC, p14) do not have sufficient sensitivity in detecting early stage disease." (PMID 29614786, 2018).
breast tumors (25 papers, 2008 to 2023). "It has been demonstrated that only 6% of breast tumors contain APC mutations and mutations in the β-catenin gene in breast cancer are very rare, despite noted Wnt-signaling abnormalities associated with 60% breast tumors." (PMID 28402277, 2017). "Up to 50% of breast tumors have hypermethylation of the adenomatous polyposis coli (APC) promoter, and transcript loss leads to hyperactivation of the Wnt pathway." (PMID 26106366, 2015). "The result was consistent with previous studies, which indicated that promoter methylation of APC could be implicated in the occurrence of breast tumors." (PMID 27191268, 2016). "This study we also analyzed altered APC mRNA expression level in fifty-one breast tumors and paired normal breast tissues by quantitative real-time reverse transcription-PCR." (PMID 33369461, 2020). "Sixty-one fresh tissues of breast tumor were evaluated for APC promoter hypermethylation with methylation-specific PCR techniques (MS-PCR) and APC mRNA expression level analysis by quantitative real-time reverse transcription-PCR." (PMID 33369461, 2020). "Sixty-one breast tumor samples, were evaluated by methylation-specific PCR, to detect promoter hypermethylation of the APC gene." (PMID 33369461, 2020). "From the 1381 primary breast tumors in METABRIC, loss (copy number <2) of APC, located on 5q22.2, was observed in 96 (6.9%) and loss of APC2 on 19p13.3 in 118 (8.5%)." (PMID 27694902, 2017). "Aberrant methylation of the adenomatous polyposis coli (APC) gene promoter occurs in about 40% of breast tumours and has been correlated with reduced APC protein levels." (PMID 18841156, 2008). "When we compared methylation frequencies of breast tumours, a higher frequency of APC promoter methylation was found in IBC (71%) when compared to non-IBC (43%) (P=0.047; χ2)." (PMID 18841156, 2008). "APC promoter methylation also occurs in a significant number of primary breast tumours (ranging from 28 to 53% of cases, depending on the applied technology)." (PMID 18841156, 2008). "We compared promoter methylation status of APC defined by qMSP to loss of mRNA expression assessed by qRT–PCR in 52 of 54 (96%) breast tumour samples (including 19 IBC and 34 non-IBC)." (PMID 18841156, 2008). "The frequency of APC methylation in primary breast tumours increases with tumour stage and size." (PMID 18841156, 2008). "Furthermore, we compared APC methylation levels in matched normal appearing breast tissue and primary breast tumour." (PMID 18841156, 2008). "Hypermethylation of the APC gene promoter was observed in 28 of 51 (55%) breast tumours." (PMID 18841156, 2008). "Finally, there was low sensitivity for APC methylation to detect breast tumors." (PMID 27191268, 2016). "Finally, heterozygous mutation of APC in immature, but not mature, mammary epithelium induces breast tumors." (PMID 25406066, 2014). "Furthermore, hypermethylation of RASSF1A was more frequently present in adjacent normal breast tissues from advanced stage breast tumors (P Χ2 = 0.01) and hypermethylation of APC was more frequently present in adjacent normal breast tissues from breast tumors expressing ER (P Χ2 = 0.04)." (PMID 20226036, 2010). "Notably, APC methylation levels in ‘normal’ tissue from cancer patients were significantly higher than in breast tissue from unaffected women and in some cases values as high as those observed in breast tumour tissue were measured." (PMID 18841156, 2008). "APC (adenomatous polyposis coli), initially described as a tumor suppressor gene, has been shown to co-immunoprecipitate with MUC1 in human breast tumors and metastasis." (PMID 35625825, 2022). "In our study methylation of the BRCA1, APC and RASSF1A promoter regions was analyzed in 75 paired breast tumor and PB DNA samples using the MS-HRM (Methylation Sensitive High Resolution Melting) protocol." (PMID 22129206, 2011).
breast tumors (continued). "We have examined methylation status of the BRCA1, APC and RASSF1A promoter regions in a panel of 75 breast tumor and PB DNA samples from the same individual." (PMID 22129206, 2011). "The methylation levels of APC in samples from non-neoplastic tissue adjacent to a breast tumour correlated with that observed in samples of the corresponding tumour tissue (trend for statistical significance)." (PMID 18841156, 2008). "To evaluate epigenetic differences in tumor-related genes relating to ER and HER2/neu status of primary tumors, we examined the promoter methylation status of the promoter region CpG islands of eight major breast tumor-related genes (RASSF1A, CCND2, GSPT1, TWIST, APC, NES1, RARβ2, and CDH1)." (PMID 18485221, 2008). "Two cell surface markers (EpCAM-Pecy7 and CD49f-APC) were used to identify 2 cell subsets using FACS, namely, basal/stem cells (TICs, CD49fhighEpCAMlow, approximately 57.6 %) and luminal cells (NTCs, CD49flowEpCAMhigh, approximately 34.1 %) in primary breast tumor, as reported in a previous study." (PMID 26695440, 2016).